ATF6 (activating transcription factor 6)
Diseases named in the same sentence as ATF6 in open-access papers (continued):
Sharing a sentence is not in itself a finding about the gene and the disease.
amyotrophic lateral sclerosis (8 papers, 2018 to 2023). Amyotrophic lateral sclerosis (ALS) is a neurodegenerative disease characterized by progressive muscular paralysis reflecting degeneration of motor neurons in the primary motor cortex, corticospinal tracts, brainstem and spinal cord. "In models for amyotrophic lateral sclerosis and cone dystrophy, ATF6 reporter expression is induced in spinal cord interneurons or photoreceptors, respectively, suggesting a role for ATF6 response in multiple neurodegenerative diseases." (PMID 31852729, 2020). "ATF6 was also found to be strongly activated in AD and amyotrophic lateral sclerosis (ALS) individuals in pathways related to endoplasmic reticulum homeostasis." (PMID 37953885, 2023). "Furthermore, ATF6 is known as a brain biomarker for various nervous system diseases, including amyotrophic lateral sclerosis (ALS), Alzheimer’s disease (AD), and neonatal hypoxic–ischemic encephalopathy, but whether ATF6 can be used as a biomarker of schizophrenia has not been reported." (PMID 37376599, 2023). "Amyotrophic lateral sclerosis (ALS) patients show increased PERK, ATF6, and IRE1 signaling, with higher levels of CHOP and BiP in the spinal cord, and increases in downstream elements of the UPR such as ATF4, XBP-1, and GRP58." (PMID 34360909, 2021). "In amyotrophic lateral sclerosis (ALS), the expression level of the three major components of the UPR, PERK, IRE1, and ATF6 is increased in the spinal cord of patients." (PMID 29511163, 2018).
atherosclerosis (8 papers, 2012 to 2025). A disease characterized by the build-up of fatty material and calcium deposition in the arterial wall resulting in partial or complete occlusion of the arterial lumen. "Both oxidized LDL and phospholipolyzed LDL can induce endoplasmic reticulum stress in endothelial cells with ATF6 activation, and this process has been implicated in the initiation of vascular inflammation with progression of atherosclerosis." (PMID 23285140, 2012). "Furthermore, aPC treatment prevented the glucose-induced cleavage of ATF6α, which has been associated with atherosclerosis." (PMID 41083981, 2025). "Prolonged ER stress has been demonstrated by the activation of UPR signal transducers, notably IRE-1 and ATF-6, in endothelial cells isolated from atherosclerosis-prone arteries." (PMID 36014347, 2022). "Thus, our findings of significantly lower levels of miR-149-5p in stable CAD patients support its active role in the development of atherosclerosis through regulating genes involved in the lipid metabolism as well as suppressing STAT3- or ATF6-mediated inflammation." (PMID 36717592, 2023). "In addition, a newly discovered myokine that protects against metabolic disorders and atherosclerosis, irisin, was shown to inhibit the PERK/eIF2α/CHOP and ATF6/CHOP ER stress signaling pathways, thereby alleviating the apoptosis of cultured RAW264.7 macrophages induced by ox-LDL." (PMID 32963706, 2020). "Recently, a study of atherosclerosis showed that laminar flow protected ER stress-induced cleaved forms of PARP-1 and caspase-3 and inhibited the ER stress-induced p-eIF2α, ATF4, CHOP, spliced XBP-1, ATF6, and JNK pathways to protect endothelial cells from apoptosis." (PMID 31506423, 2019).
diabetic nephropathy (8 papers, 2014 to 2024). "Our previous study showed that in a T1DM diabetic nephropathy mouse model, a reduction in nuclear XBP1s associated with increased nuclear ATF6 and CHOP in kidney was apparent at 10 weeks and peaked at 26 weeks post STZ injection and coincided with the onset of albuminuria." (PMID 34421344, 2021). "An ATF6-dependent maladaptive ER response induced by impaired XBP1s nuclear translocation was observed in diabetic nephropathy." (PMID 35765067, 2022). "However, ATF6 overexpression in podocytes increased diabetic nephropathy through ATF6-dependent CHOP activation." (PMID 33558590, 2021). "The severity of diabetic nephropathy and levels of CHOP and ATF6 were exaggerated in podocyte-specific Xbp1-knockout mice and in transgenic mice overexpressing ATF6 in podocytes." (PMID 38778209, 2024). "Mice with diabetic nephropathy (either induced by STZ or in db/db mice) showed increased levels of CHOP and activated ATF6 in the renal cortex." (PMID 38778209, 2024). "GRP78 serves as a master regulator of the UPR sensors, ATF6, IRE1α, as well as PERK, and plays an important role in the progression of diabetic nephropathy." (PMID 24667182, 2014).
endothelial dysfunction (8 papers, 2018 to 2025). In vascular diseases, endothelial dysfunction is a systemic pathological state of the endothelium (the inner lining of blood vessels) and can be broadly defined as an imbalance between vasodilating and vasoconstricting substances produced by (or acting on) the endothelium. "Additionally, PTPN1 and ATF6 expressions were correlated with ET1 which codes for a protein associated with septic endothelial dysfunction." (PMID 31737637, 2019). "The aim of the study is to investigate the involvement of activating transcription factor 6 (ATF6) in the protective effects of OCT in endothelial dysfunction." (PMID 39770448, 2024). "ASCs effectively alleviated endothelial dysfunction under hypoxic conditions by strengthening ATF6 and initiating a transcriptional program to restore ER homeostasis." (PMID 38139026, 2023). "Treadmill exercise training suppressed ER stress (PERK, IRElα, and ATF6) and ameliorated endothelial dysfunction through a PPARγ-dependent mechanism with an increase in NO bioavailability in diabetic arteries." (PMID 33329050, 2020). "ERS induces endothelial dysfunction in vivo and we found that the variation in ATF6 expression was correlated with the variation in endothelial dysfunction marker." (PMID 31737637, 2019). "Moreover, in a previous study conducted in septic patients, we have shown an association between expressions of ATF6 and ET1 (coding for endothelin-1 which is associated with endothelial dysfunction)." (PMID 33659258, 2020). "The present study reveals that ATF6 activation enhances the barrier-enhancing effects of OCT, presenting a promising approach for mitigating endothelial dysfunction in lung inflammatory diseases." (PMID 39770448, 2024). "Quantitative PCR (performed from whole blood) evaluated the expression of genes coding for PTP1B (PTPN1) and key elements of ERS (GRP78, ATF6, CHOP) or for endothelial dysfunction-related markers (ICAM1 and ET1)." (PMID 31737637, 2019). "We have shown that PTP1B and ATF6 might be correlated with organ failure (SOFA score) and endothelial dysfunction (ET1 expression)." (PMID 31737637, 2019).
myeloma (8 papers, 2011 to 2026). "This duality indicates a potentially powerful target, identifying ATF6 as an understudied aspect of myeloma." (PMID 23781234, 2013). "One group has performed specific knockdown of ATF6 in myeloma cells and shown that, as is also the case for the other ER stress sensors, targeted loss resulted in significant cell death." (PMID 23781234, 2013). "Indeed, the transcriptome of ATF6 should itself be a discrete target of research in the myeloma field." (PMID 23781234, 2013). "As illustrated in the literature, myeloma cells resistant to Bz have reduced dependence on the UPR, reflected by the substantial decreases in XBP-1 and ATF6 expression." (PMID 34943972, 2021). "In CCC but not in multiple myeloma, the ATF6 pathway was significantly upregulated compared with the normal ovary (P < 2.22 × e−16)." (PMID 40459063, 2025). "The ATF6 protein was not detectable in three of the human myeloma cell lines tested (LP-1, H929 and OPM2) and was not analysed further." (PMID 28467788, 2017). "17-AAG treatment to myeloma cells induced splicing of XBP1, upregulation of CHOP, and activation of ATF6, and induced cell death with activation of JNK and caspase cleavage, indicating that HSP90 inhibitors induce myeloma cell death in part via ER stress and UPR pathway." (PMID 23050960, 2012).
myopia (8 papers, 2015 to 2025). "We showed that ER stress and/or UPR pathways, especially PERK and ATF6, are also associated with an increase in the size of the eyeball during myopia development as in the other organs." (PMID 36216837, 2022). "Among these, PERK-eIF2 and ATF6 signaling are implicated in myopia development." (PMID 40598091, 2025). "Notably, both 0.5% and 2% 4-PBA eye drops suppressed activation of the PERK and ATF6 pathways associated with myopia progression in LIM." (PMID 40598091, 2025). "Recent studies have confirmed that scleral endoplasmic reticulum stress and the PERK/ATF6 pathway control axial elongation in a mouse model of myopia." (PMID 39448852, 2025). "Based on these results, we assumed that scleral PERK and/or ATF6 dysregulation resulted in axial elongation and the myopia onset/development." (PMID 36216837, 2022). "Taken together, these results suggest that among the three major effector proteins of the UPR pathway, PERK, and ATF6, possibly mainly ATF6, are involved in myopia onset/progression." (PMID 36216837, 2022). "Regarding the involvement of ATF6 in myopia, there was some discrepancy between the results using inhibitors and the results of gene knockdown using the CRISPR/Cas9 system." (PMID 36216837, 2022). "LIM activated all IRE1, PERK and ATF6 axis, and pharmacological inhibition of both PERK and ATF6 suppressed myopia progression, which was confirmed by knocking down above two genes via CRISPR/Cas9 system." (PMID 36216837, 2022). "However, axial elongation and myopia occurred in all groups in which ATF6 activation was observed, strongly suggesting the involvement of ATF6." (PMID 36216837, 2022). "BPA administration activated scleral PERK and ATF6 pathways, and 4-PBA eye drops attenuated ER stress response and suppressed myopia progression." (PMID 37746069, 2023). "BPA controlled axial elongation during myopia development in a mouse model by inducing scleral ER stress and activation of the PERK/ATF6 pathway." (PMID 37746069, 2023). "Here, we show that endoplasmic reticulum (ER) stress in sclera is an essential regulator of axial elongation in myopia development through activation of both PERK and ATF6 axis followed by scleral collagen remodeling." (PMID 36216837, 2022). "We demonstrate that scleral ER stress and PERK/ATF6 pathway controls axial elongation during the myopia development in vivo model and 4-PBA eye drop is promising drug for myopia suppression/treatment." (PMID 36216837, 2022). "Real-time PCR and Western blotting were performed to detect the expression of GRP78, p-eIF2α, spliced XBP1, ATF6, ATF4 and p-IRE1α in the lenses of normal human subjects and patients with age-related, myopia-related or congenital cataracts." (PMID 26091066, 2015). "In the lenses of the age-related and high myopia-related cataract groups, the protein levels of ATF6, p-eIF2α and p-IRE1α and the gene expression levels of spliced XBP1, GRP78, ATF6 and ATF4 were greatly increased." (PMID 26091066, 2015). "On the other hand, ATF6 knockdown showed no myopia in either non-myopia-induced or myopia-induced eyes." (PMID 36216837, 2022). "Mixed inhibitor eye drops experiments showed that simultaneous inhibition of PERK and ATF6 inhibited myopia induced by minus lens wearing, whereas other combinations did not inhibit myopia progression, but rather induced axial elongation in non-myopia induced eyes." (PMID 36216837, 2022). "Although ATF6 activation showed a non-significant trend, the overall findings underscore the potential of 4-PBA in mitigating scleral ER stress and myopia progression." (PMID 40598091, 2025).
ovarian carcinoma (8 papers, 2016 to 2025). A malignant neoplasm originating from the surface ovarian epithelium. "In this study, we found an increase in GRP78 and ATF6 ER stress markers in both wild-type and chemoresistant ovarian cancer cell lines." (PMID 40506749, 2025). "The inhibitor of DNA binding 1 (ID1), significantly increased in our platinum-resistant PDOs, has been described to induce autophagy and chemoresistance through the STAT3/ATF6-mediated signalling pathway in ovarian cancer." (PMID 37686015, 2023). "In this report, we have identified that ID1 confers ovarian cancer cell chemoresistance through the ATF6-mediated induction of autophagy, which is a novel discovery in our study." (PMID 32080166, 2020). "The data from TCGA database indicated a positive correlation between ID1 and ATF6 in tissues from ovarian cancer patients treated with platinum." (PMID 32080166, 2020). "In this study, we have identified that ID1 confers ovarian cancer chemoresistance largely through the induction of the IL-6/STAT3/ATF6-mediated autophagy." (PMID 32080166, 2020). "The involved molecules, including ID1, STAT3, and ATF6, may have a potential to be targeted in combination with chemotherapeutic agents to improve ovarian cancer survival." (PMID 32080166, 2020). "More experiments were designed to detect whether the alteration of ATF6 could change the sensitization of ovarian cancer cells to chemotherapeutic agents." (PMID 32080166, 2020). "Finally, among 396 ovarian carcinomas evaluated for ATF6, 167 (42.3%) expressed strong levels, 197 (49.9%) moderate, and 31 (7.8%) showed weak staining." (PMID 32034256, 2020). "ATF6α expression levels correlated with the proliferation or apoptosis of cancer cells and the increased ATF6α levels promote the growth and proliferation of tumor cells, including ovarian cancer and endometrial adenocarcinoma cells." (PMID 27717400, 2016). "ID1, STAT3, and ATF6 may be targeted in combination with chemotherapy for ovarian cancer treatment." (PMID 32080166, 2020). "Herein, we review the current research on the response and ovarian cancer, discussing the key sensors (IRE1, PERK, ATF6), and the conditions under which it occurs (Ca2+ homeostasis disruption, hypoxia, others)." (PMID 39319052, 2024). "The UPR is executed by three ER stress sensors‐ inositol‐requiring enzyme 1 (IRE1), activating transcription factor 6 (ATF6), and RNA‐dependent protein kinase (PKR)‐like ER kinase (PERK) and all these ER stress sensors are activated by quercetin in ovarian cancer." (PMID 31568659, 2020). "Cells with high expression of ID1 and ATF6 appeared with higher IC50 values of cispaltin and taxol, indicating that both molecules could be targeted to improve the treatment efficacy of ovarian cancer." (PMID 32080166, 2020). "We found that hyptolide inhibited cell viability in ovarian cancer cell lines, regardless of their chemoresistance, and these effects were mediated by ER stress and the activation of GRP78 and ATF6." (PMID 40506749, 2025).
ZIKV infection (8 papers, 2018 to 2023). "Future research should clarify the role of IRE1 and ATF6 pathways to LD in the context of ZIKV infection." (PMID 37208782, 2023). "Phosphorylation of one of the sensors, PERK, facilitates ZIKV infection in synergy with the ATF6 pathway at early phase of infection, whereas the ATF6 pathway facilitates late phase of infection." (PMID 34106769, 2021). "ATF6 has been shown to be upregulated in nervous tissue in a mouse model for ZIKV infection and likely contributes to neuropathogenesis." (PMID 34834970, 2021). "We found that, following ZIKV infection, ATF6n expression was moderately upregulated at the protein level, and atf6 at the mRNA level." (PMID 30241539, 2018). "Likewise, 4-phenylbutyric acid inhibits ZIKV replication by attenuating the PERK and ATF6 pathways and potentiating the IRE1α pathway, suggesting that ZIKV infection is differentially and temporally regulated by different UPR arms." (PMID 34106769, 2021). "We therefore sought to study the role of ATF6 in ZIKV infection." (PMID 34106769, 2021). "However, compared with PERK and IRE1 pathways, ATF6 has remained understudied and thus, more studies on the role of ATF6 during ZIKV infection are needed to better understand the role of this ER stress-related pathway on viral replication and pathogenesis." (PMID 32106582, 2020). "IRE1-XBP1 and ATF6 pathways are mainly activated during ZIKV infection in vitro and in vivo." (PMID 30241539, 2018). "It is still inconclusive whether ZIKV infection activates ATF6." (PMID 34106769, 2021). "ZIKV infection has been shown to activate the UPR via ATF6, where ATF6 proteolysis and ATF6n nuclear translocation were induced in vitro and in vivo." (PMID 31959174, 2020). "According to the latest reports, ZIKV infection significantly upregulates phosphorylated IRE1α and XBP1 mRNA splicing as well as ATF6 activation in mice cerebellum, indicating a tissue dependency in the UPR activation profile." (PMID 32106582, 2020). "We found that ZIKV infection in neural cells activated the IRE1-XBP1, PERK-eIF2α, and ATF6 pathways respectively." (PMID 30241539, 2018). "In the present study, we found that ZIKV infection activated ER stress both in vitro and in vivo, showing that the expression of ER stress markers, namely, BIP, cleaved ATF6, phospho-IRE1, and phospho-eIF2α, significantly increased." (PMID 30241539, 2018). "In the current study, however, we observed that ZIKV infection activated the IRE1-XBP1 and ATF6 pathways in the mouse nervous tissues in vivo and human neural cell line in vitro." (PMID 30241539, 2018). "Nevertheless, we detected a significant level of p50nATF6, 5%, at 24 hpi, which was completely inhibited by a specific ATF6 cleavage inhibitor, Ceapin-A7, at a noncytotoxic level, confirming ATF6 activation in ZIKV infection." (PMID 34106769, 2021). "Our results reveal that ATF6 and BIP upregulated during ZIKV infection in vitro and in vivo." (PMID 30241539, 2018). "Thus, the ATF6 pathway appears to be little or not active, depending on the model and potentially inhibited during ZIKV infection." (PMID 35163212, 2022). "This indicates that ATF6 or other UPR arms are not the sole pathway modulating ZIKV infection and they may act in cooperation or in opposition." (PMID 34106769, 2021). "During ZIKV infection, not all PERK, ATF6, and IRE1 pathways of the UPR are activated in the same way in all models." (PMID 35163212, 2022).
Glucose intolerance (7 papers, 2015 to 2024). Glucose intolerance (GI) can be defined as dysglycemia that comprises both prediabetes and diabetes. "Studies in Dutch Caucasian populations also reported that ATF6 SNPs are significantly associated with glucose intolerance and the development of T2DM." (PMID 36613674, 2022). "ATF6, a second UPR sensor, is also important for β-cell function as ATF6alpha-null mice on high-fat diet exhibit glucose intolerance due to pancreatic β-cell failure." (PMID 38966213, 2024). "Consistently, ATF6 overexpression in obese or diabetic livers regulates blood glucose level, reduces glucose intolerance and ameliorates insulin sensitivity." (PMID 37020593, 2023). "In line with this, whole‐body deletion of ATF6 impaired glucose intolerance and blunted insulin secretion, whereas ATF6 induction improved β cell insulin secretion and viability under ER stress conditions." (PMID 37303813, 2023). "There is also evidence that Atf6α-null mice subjected to high-fat diet develop glucose intolerance and after ischemic stroke have greater size of brain infarcts, both of which are explained by conditions of ER stress." (PMID 26063662, 2015). "In current study, ATF6−/− mice showed glucose intolerance and impaired insulin sensitivity." (PMID 38007457, 2023). "Indeed, hepatocyte‐specific overexpression of ATF6α reduced hepatic glucose output and steatosis, while its whole‐body deletion exacerbated glucose intolerance." (PMID 37303813, 2023).